FAP (fibroblast activation protein alpha)
Diseases named in the same sentence as FAP in open-access papers (continued):
Sharing a sentence is not in itself a finding about the gene and the disease.
pancreatic cancer (131 papers, 2011 to 2026). "For example, targeting CXCL12 to antagonize the development of pancreatic cancer associated with FAP-expressing cancer-associated fibroblasts." (PMID 40264753, 2025). "In accordance with previously reported, FAP was highly expressed in cancer cells and fibroblasts of pancreatic cancer tissues, and its high expression was associated with desmoplasia and results in poor prognosis." (PMID 40457405, 2025). "From this risk model, we can see that the upregulation of COL10A1/FAP/FN1 expression is a risk factor for pancreatic cancer, and the upregulation of all three increases the risk of developing PC in patients." (PMID 38063927, 2023). "The results showed that, compared with the other four candidate aptamers, aptamer AptFAP-A4 had a higher affinity for human pancreatic cancer-associated fibroblasts with high FAP protein expression at the cellular level." (PMID 36838669, 2023). "When FAP+ cells were depleted in lung or pancreatic cancers, it caused immediate growth arrest of immunogenic tumor through TNF-α- and IFN-γ-mediated mechanism." (PMID 35222418, 2022). "FAPα overexpression has been associated with poor prognosis as occurs, among others, in rectal, hepatocellular, colon, and pancreatic cancers." (PMID 36555218, 2022). "We first developed dual-targeting (anti-EGFR and anti-FAP) irinotecan liposomes for both pancreatic cancer cells and tumor-associated fibroblasts." (PMID 35745775, 2022). "In pancreatic cancer, FAP-targeted radiotracers have been proposed as a diagnostic and therapeutic tool." (PMID 36263225, 2022). "High expression of FAP is associated with shorter overall survival and disease-free survival in pancreatic cancer patients." (PMID 33572223, 2021). "For example, in pancreatic cancer, dense in stromal tissue, a mouse model has shown depletion of carcinoma-associated fibroblast expressing fibroblast activation protein (FAP), restores sensitivity to checkpoint blockade." (PMID 31973059, 2020). "Compared with low FAP expression, the pooled analyses of the two pancreatic cancer studies indicated that FAP overexpression was associated with a greater detrimental outcome (HR: 3.18, 95% CI: 1.42–7.12, P = 0.005)." (PMID 25775399, 2015). "As the mechanisms underlying these clinical results, FAP-expressing fibroblasts promoted the invasiveness and activated cell cycle of a pancreatic cancer cell line in vitro." (PMID 26330349, 2015). "Second, the pooled analyses of colorectal cancers or pancreatic cancers all indicated that FAP overexpression was associated with a detrimental OS (HR: 1.72, P = 0.009; HR: 3.18, P = 0.005, respectively)." (PMID 25775399, 2015). "We elucidated a potential molecular mechanism underlying the enhanced pancreatic cancer cell motility mediated by FAP+ matrix." (PMID 21668992, 2011). "Fibroblast activation protein (FAP) is specifically overexpressed in pancreatic cancer-associated fibroblasts (CAFs), which are the major cell component of the tumor microenvironment in pancreatic cancer." (PMID 38360704, 2024). "Moreover, high FAP expression is shown in GC 39, esophageal squamous cell carcinoma 40, colorectal cancer 41, pancreatic cancer 42, and non-small cell lung adenocarcinoma 43, and linked with poor prognosis." (PMID 36632455, 2023). "Finally, Cy5-labeled aptamers were co-incubated with human pancreatic cancer-associated fibroblasts highly expressing FAP protein, and confocal microscopy imaging showed that aptamer AptFAP-A4 had the highest affinities with the cells." (PMID 36838669, 2023). "Here, we show that FAP + melanoma-associated fibroblasts display an immunosuppressive, arguably tumor promoting phenotype, which is in line with observations of others made in colorectal and pancreatic cancers." (PMID 32328671, 2021).
pancreatic cancer (continued). "However, in another study, infusion of FAP CAR T cells led to bone toxicity and cachexia in non-tumor bearing wild-type mice as well as in global Rag1-deficient mice bearing a stroma-rich pancreatic cancer xenograft with strong FAP-positivity." (PMID 33572223, 2021). "Blockade of FAP in combination with radiation treatment in murine models of pancreatic cancer was associated with antigenic specific tumor T cell infiltrate and enhanced collagen deposition but it did not prolong survival even when combined with anti-PD1 therapy." (PMID 32466266, 2020). "FAP was shown to increase stromal cell proliferation and invasiveness, to reduce apoptosis, and to be associated with worse prognosis in colon cancer and pancreatic cancer." (PMID 29245907, 2017). "More importantly, FAP is recognized as a marker of CAFs, and is reported to increase stromal cell proliferation and invasiveness, reduce cell apoptosis, and to be associated with worse prognosis in colon cancer and pancreas cancer." (PMID 25126747, 2014). "Furthermore, to investigate the influence of FAP aptamers on cell growth, human pancreatic cancer-associated fibroblasts and Ramos cells were co-incubated with 1 μmol/L each of the five candidate aptamers for 24 h, and cell viability was subsequently detected and calculated using a CCK8 assay." (PMID 36838669, 2023). "We also describe the functional role of FAP-overexpressing stromal cells, particulary CAFs, in tumor immuno- and metabolic microenvironments, and summarize the mechanisms underlying the contribution of FAP-overexpressing CAFs in pancreatic cancer progression and treatment resistance." (PMID 36263225, 2022). "However, FAP is expressed on the surface of carcinoma-associated fibroblasts in the tumor stroma in more than 90% of solid tumors including breast, colorectal, skin, and pancreatic cancers, and in some soft tissue sarcomas." (PMID 35874707, 2022). "In addition, although colorectal cancer or pancreatic cancer was associated with FAP overexpression and poor survival, sensitivity analysis by tumor type indicated that the effect was not statistically significant compared with that in non-colorectal cancers or non-pancreatic cancers." (PMID 25775399, 2015). "Characterization of FAP+ mesenchymal cell heterogeneity in pancreatic cancer identifies a tumor-suppressive interferon-response cancer-associated fibroblast subtype that can be induced by stimulating type I interferon signaling using STING agonists." (PMID 40215177, 2025). "The FAPI PET uptake and FAP immunostaining intensity have been suggested to be related to malignancy in pancreatic tumors." (PMID 40126602, 2025). "Several FAP‐TRTs are currently being applied to various cancer types, including pancreatic cancer, lung cancer, and gastrointestinal tumors." (PMID 40656546, 2025). "The attempts to block FAP+ have shown some promises in inducing tumor necrosis and immune-responsive cytotoxicity when combined with immune checkpoint blockade in pancreatic cancer mouse models." (PMID 40069574, 2025). "An anti-fibroblast activation protein (FAP) antibody conjugated to IRDye®700DX (αFAP-IR700) was tested on pancreatic cancer cells and hPSC-5 (CAFs)." (PMID 40361512, 2025). "In mouse models of pancreatic cancer, the ablation of FAP+α‐SMA+ CAFs paradoxically resulted in accelerated tumor progression and increased infiltration of Treg cells." (PMID 40656546, 2025). "In a 2020 study, lipid–albumin nanoparticles engineered to release paclitaxel in response to FAPα demonstrated enhanced tumor penetration and robust tumor regression in a pancreatic cancer mouse model, with minimal systemic toxicity." (PMID 41441395, 2025). "In pancreatic cancer, multiple FAP‐targeted probes, such as TEFAPI‐06 and 07, as well as 177Lu–FAPI‐46, have demonstrated improved tumor retention and significant tumor growth inhibition in mouse models." (PMID 40656546, 2025).
pancreatic cancer (continued). "Recent studies suggest that FAP-targeted therapy can inhibit the proliferation of pancreatic tumor cells." (PMID 39055892, 2024). "For the TRT of pancreatic cancer, the specificity of pancreatic cancer biomarkers, such as FAP, is conducive to the improvement of the radiopharmaceutical uptake ratio of tumor-to-normal tissue." (PMID 38360704, 2024). "In an orthotopic, syngeneic mouse model of pancreatic cancer, FAP-IL-2v exhibited synergistic effects when combined with a murine anti-PD-L1 antibody, significantly improving the survival of mice compared to monotherapy with the anti-PD-L1 antibody." (PMID 38558814, 2024). "Given the high proportion of desmoplastic stroma in pancreatic cancer and tumor cell FAP expression, it is expected to show intense FAP expression." (PMID 38540204, 2024). "A type II transmembrane serine protease, FAP, is highly expressed on CAFs, particularly in tumors exhibiting substantial desmoplasia like pancreatic cancer." (PMID 38540204, 2024). "Recently, a liposomal irinotecan combined with an anti-EGFR/FAP bispecific antibody demonstrated improved efficacy in pancreatic cancer xenograft models." (PMID 39033209, 2024). "More cells with stronger staining of ACTA2 and FAP were found in a MICAL2high patient with pancreatic cancer compared with a MICAL2low patient." (PMID 38326344, 2024). "To improve the poor accumulation of CLDN18.2-targeted CAR-T cells in pancreatic cancer revealed in our previous study, we developed one kind of novel FAP-targeted CAR-T cells." (PMID 37046312, 2023). "Pancreatic tumor stroma is high in cancer-activated fibroblasts, which express FAP, alpha-smooth muscle actin, and other biomarkers." (PMID 37242560, 2023). "Fibroblast activation protein alpha (FAPα) is a marker of cancer-associated fibroblasts (CAFs), which are abundant in the TME of pancreatic cancer." (PMID 37601380, 2023). "Preclinical investigations have explored various approaches, including FAP deletion through LacZ knock-in or Diphtheria toxin targeting FAP+ CAFs in lung cancer, colon cancer, and pancreatic cancer xenograft models, demonstrating notable antitumor efficacy." (PMID 37784157, 2023). "FAP-α overexpressing fibroblasts were found to promote pancreatic cancer cell invasion by remodeling the stromal extracellular matrix." (PMID 36937451, 2023). "In colorectal cancer, ovarian cancer, non-small cell lung cancer, high-grade invasive uroepithelial carcinoma of the bladder, pancreatic cancer, and melanoma, FAP+CAFs also predict a poorer prognosis for patients." (PMID 37277751, 2023). "In the pancreatic cancer, the deletion of FAP gene can significantly reduce the infiltration of FAP+ CAFs and induce tumor hypoxic necrosis." (PMID 37064113, 2023). "Consistent with this expectation, FAP IHC scoring demonstrated strong FAP expression in 50–100% of pancreatic cancer cases." (PMID 37608378, 2023). "Several groups have reported the impact of FAP in pancreatic cancer progression and its use in developing targeted drug delivery systems." (PMID 37242560, 2023). "A depletion of FAP-expressing fibroblasts in in vivo experiments for pancreatic cancer showed synergisms with anti-PD-L1 therapy and led to tumor suppression." (PMID 37046710, 2023). "It was found that FAP is overexpressed in pancreatic cancer stromal tissues compared to normal tissues by using tissue microarray analysis." (PMID 37316886, 2023). "Several tumors also showed a similar phenomenon, suggesting that FAP is a potential target for fibroblast-rich tumors, including pancreatic cancer." (PMID 37046312, 2023). "Pancreatic cancer cells released Transforming growth factor beta 1 (TGFβ1) and induced Pancreatic stellate cells (PSCs) to express FAP." (PMID 37316886, 2023). "Expression of fibroblast activation protein (FAP) is a vital characteristic of active CAFs, including pancreatic cancers." (PMID 37046312, 2023).
pancreatic cancer (continued). "Overexpression of FAP in the tumor microenvironment facilitated the specific accumulation and release of the nab-paclitaxel in pancreatic cancer models." (PMID 37242560, 2023). "In a mouse model of pancreatic cancer, FAP+ CAFs are the main source of CXCL12 that combines with CXCR4 on the surface of cancer cells and marginalized T cells through a CXCL12–CXCR4 signaling mechanism, leading to tumor immunosuppression." (PMID 37143134, 2023). "Most malignancies express FAP in the tumour micro-environment, while some cancers express FAP on their cellular membrane (e.g., sarcoma, certain ovarian, and pancreatic cancers)." (PMID 39355052, 2023). "Based on the expression levels of COL10A1/FAP/FN1, we further constructed a nomogram risk model for pancreatic cancer." (PMID 38063927, 2023). "The purpose of this study was to compare the therapeutic effects of [177Lu]-labelled and [225Ac]-labelled FAPI in FAP-expressing pancreatic cancer xenografts." (PMID 34537893, 2022). "This study suggested the possible application of FAPI radioligand therapy in FAP-expressing pancreatic cancer." (PMID 34537893, 2022). "Our previous study labelled FAPI-04 with 225Ac, an alpha particle emitter with a half-life of 10 days for its first decay, and investigated the therapeutic effects of [225Ac]FAPI-04 in FAP-expressing human pancreatic cancer." (PMID 34537893, 2022). "Our previous study used 64Cu and 225Ac-labelled FAP inhibitors (FAPI-04) for a FAP-expressing pancreatic cancer xenograft imaging and therapy." (PMID 34537893, 2022). "Inhibition of molecular markers of CAFs, such as α-SMA and fibroblast activation protein (FAP), can disrupt desmoplasia in the pancreatic tumor microenvironment and block tumor growth." (PMID 36143975, 2022). "The levels of αSMA, PDGFRβ and FAP in melanoma and pancreatic tumours were nearly undetectable in Atf4Δ/Δ mice, which indicates that ATF4 is essential for CAF activation within the TME." (PMID 35654839, 2022). "At the cellular level, pancreatic cancer cell lines have been shown to express FAP protein to a greater or lesser extent, and mRNA at different levels." (PMID 36263225, 2022). "The finding of numerous studies have established the link between stromal-expressed FAP, particularly FAP+ CAFs, and pancreatic cancer, thereby indicating the potential ultility of FAP as a target in PAAD treatment." (PMID 36263225, 2022). "Here, a series of databases suggested that FAP expression was significantly different in pancreatic cancer compared to normal tissue." (PMID 36051919, 2022). "The findings of studies that have used murine pancreatic cancer models have tended to indicate that the adoptive transfer of FAP-CAR T can also inhibit tumor growth in an immune-independent manner." (PMID 36263225, 2022). "Similar effects were shown when FAPα was pharmacologically targeted in a transplanted pancreatic cancer model, where there was a decrease in macrophage recruitment and an increase in T-cell infiltration." (PMID 36555218, 2022). "In the pancreatic cancer microenvironment, FAP-expressing CAFs have been a major source of CXCL12, which can bind to KRT19 (cytokeratin 19) at the surface of pancreatic cancer cells." (PMID 35805064, 2022). "We demonstrated the effectiveness of alpha therapy for FAP-expressing pancreatic cancer using [225Ac]FAPI-04 in a previous study." (PMID 34537893, 2022). "A proof-of-concept study of 225Ac-FAPI-04 (as well as 64Cu-FAPI-04) in FAP-expressing pancreatic cancer xenograft mouse models suggested the applicability of FAP-targeted α-therapy in pancreatic cancer." (PMID 34168013, 2022). "Enhanced velocity and directionality of pancreatic cancer cells invading through FAP+ matrices were observed, which was effectively reversed by inhibition of FAP enzymatic activity." (PMID 35222418, 2022). "Compared with normal, the expressions of FAP have significant differences on 13 of 31 Pan-cancers, such as breast, colon, and especially pancreatic carcinomas." (PMID 36051919, 2022).
pancreatic cancer (continued). "Targeting FAP has been a topic of interest in oncology treatment, and in pancreatic cancer, blocking of FAP has led to better outcomes and also to increased infiltration of CD8 T cells." (PMID 34771664, 2021). "Meanwhile, several major components of the pancreatic cancer stroma (αSMA, fibronectin, collagen‐I, and FAP) were significantly decreased, implying that the ECM was modulated." (PMID 33783993, 2021). "As a marker of CAFs, FAP-positive CAFs contribute to immunosuppression by secreting CXCL12 in a pancreatic cancer model, enhancing recruitment of MDSCs via STAT3-CCL2 signaling and promoting the generation of Tregs and TAMs." (PMID 35155199, 2021). "Fibroblast Activation Protein (FAP) is frequently (90%) expressed, predominantly in CAFs, with pancreatic cancer patients." (PMID 38107772, 2021). "In these tumors, FAP overexpression is typically observed in the interstitium, which has led to FAP being considered a universal marker for CAFs, although FAP expression can also be detected in gastric carcinoma, pancreatic carcinoma and melanoma cells." (PMID 34490078, 2021). "Further mechanistic studies revealed that the immunomodulatory effect can be attributed to the secretion of cytokines and the alleviation of immunosuppressive components in pancreatic cancer stroma, including FAP-α and hyaluronic acid." (PMID 33634030, 2020). "Some activated CAFs in pancreatic cancer express and secrete fibroblast activated protein (FAP), which influences cancer cell motility and invasion, cancer cell cycle progression, extracellular matrix deposition, and angiogenesis within the tumor matrix." (PMID 32466266, 2020). "FAP expression in pancreatic cancer and non-small cell lung cancer is associated with worse clinical outcome." (PMID 32625204, 2020). "The intensity of FAP expression in pancreatic cancer correlates inversely with outcome such that higher expressing tumors have worse outcome." (PMID 32466266, 2020). "Inhibiting CXCL12 produced by FAP+ CAFs re-sensitizes pancreatic cancer cells to anti-PDL1 immunotherapy." (PMID 32466266, 2020). "Nonetheless, depletion of FAP+ CAFs in mice with pancreatic cancer enabled the antitumor efficacy of immune checkpoint blockade, namely anti-CTLA4 and anti-PD-L1 (CD274) antibodies." (PMID 29686035, 2018). "FAP α-induced reorganization of the ECM in TME promotes the invasiveness of pancreatic cancer cells." (PMID 26985769, 2016). "There is also growing evidence that high FAP α expression in pancreatic cancer is related to poor clinical outcome and its location is associated with its clinical results." (PMID 26985769, 2016). "In the present study we focused on stromal FAP expression in terms of the effect of stromal FAP expression on pancreatic cancer cells, and regarded FAP expressing stromal fibroblasts as CAFs." (PMID 26330349, 2015). "We also generated a fibroblastic cell line stably expressing FAP, and examined the effect of FAP-expressing fibroblasts on invasiveness and the cell cycle in MiaPaCa-2 cells (a pancreatic cancer cell line)." (PMID 26330349, 2015). "FAP-overexpressing fibroblasts have been shown to produce an extracellular matrix that enhances the invasive velocity and directionality of pancreatic cancer cells." (PMID 26330349, 2015). "To confirm the putative significance of studying FAP-expression effects in stromal matrices, we first examined FAP expression in the human pancreatic cancer patient tissues and mouse xenografts by immunohistochemistry." (PMID 21668992, 2011). "We observed that FAP is highly expressed on the stromal fibroblasts of human pancreatic cancer, while it is undetectable both in the epithelial cancer cells and normal tissue (not shown)." (PMID 21668992, 2011). "In vivo, FAP is highly expressed on pancreatic tumor stromal fibroblasts, but its expression ex vivo on cultured primary cells is not maintained." (PMID 21668992, 2011).